BACE1 (beta-secretase 1)
Diseases named in the same sentence as BACE1 in open-access papers (continued):
Sharing a sentence is not in itself a finding about the gene and the disease.
tauopathy (7 papers, 2016 to 2024). Neurodegenerative disorders involving deposition of abnormal tau protein isoforms (tau proteins) in neurons and glial cells in the brain. "APP and BACE1 have been found to be O-glycosylated and N-glycosylated in tauopathy patients' brains." (PMID 33488497, 2020). "In addition, our previous results showed that the silencing of BACE1 produces reduction of tauopathy in old 3xTg-AD mice, and part of the effect was autophagosome lipidation-dependent." (PMID 27891075, 2016). "In addition to future studies directed to further elucidation of BACE1 and γ-secretase modulation of neuronal tau pathology in vitro, it will also be important to determine whether inhibition of these enzymes leads to a reduction of tau pathology in mouse models of tauopathy." (PMID 37269953, 2023). "Enzymatic glycosylation may contribute to tauopathies by modifying proteins other than tau, such as APP and the β-site APP-cleaving enzyme 1 (BACE1)." (PMID 33488497, 2020). "Other in vivo studies revealed that quercetin decreased extracellular β-amyloidosis, tauopathy, astrogliosis, and microgliosis in the hippocampus and amygdala of 3xTg-AD mice, decreasing the number of paired helical filaments (PHF), Aβ levels, and BACE1-mediated cleavage of APP." (PMID 35955963, 2022).
brain injury (6 papers, 2007 to 2020). Acute and chronic (see also brain INJURIES, CHRONIC) injuries to the brain, including the cerebral hemispheres, CEREBELLUM, and brain STEM. "In addition to inflammation other conditions may cause BACE1 expression to increase in the brain, including oxidative stress, traumatic brain injury (TBI), hypoxia and ischemia." (PMID 18005427, 2007). "Data derived from a rat model of TBI supports a role for BACE1 elevation in the increase of Aβ levels observed in patients with brain trauma." (PMID 18005427, 2007). "BACE1 cleaves a variety of substrates and is associated with decreased dendritic spine integrity and axonal blebbing, which is due to an increase in the number of APP positive neuronal terminals after brain trauma." (PMID 33071724, 2020). "Further support for the role of BACE1 in response to stress comes from observations of BACE1 elevation following traumatic brain injury (TBI), following which, increased levels of BACE1 mRNA in hippocampal and cortical neurons were detected." (PMID 19415126, 2007).
Cerebral ischemia (6 papers, 2012 to 2022). Restriction of arterial blood supply to the brain associated with insufficient oxygenation to support the metabolic requirements of the tissue. "Evidence therefore suggests that various forms of dysregulation of the APP, BACE1 and PSEN1 and PSEN2 genes are associated with individual neuronal cell responses in the CA1 and CA3 areas of the hippocampus and temporal cortex with reversible cerebral ischemia." (PMID 35741821, 2022). "BACE1 levels have been shown to increase in cells exposed to oxidative stress, apoptosis, in in vivo animal models following TBI, cerebral ischemia and impaired energy metabolism." (PMID 29391027, 2018).
metabolic syndrome (6 papers, 2006 to 2024). A cluster of metabolic risk factors for CARDIOVASCULAR DISEASES and TYPE 2 DIABETES MELLITUS. "PPARγ agonists regulate multiple processes, including Aβ homeostasis through the suppression of BACE1 expression, energy metabolism, insulin sensitivity, dyslipidemia, and microglial inflammatory responses." (PMID 25356910, 2014). "Meanwhile, in a rat model of sucrose-induced metabolic syndrome (MetS), activated oxidative stress was found to promote the synthesis of amyloid precursor protein (APP) and Aβ by increasing the activity of β-site APP cleaving enzyme 1 (BACE-1)." (PMID 38327496, 2024). "In this study, the expression level of BACE1 was significantly up-regulated in the brains of OVX + HCD rabbits, which may be related to dyslipidemia induced by low estrogen level after the menopause." (PMID 30909491, 2019).
glioma (5 papers, 2019 to 2025). A benign or malignant brain and spinal cord tumor that arises from glial cells (astrocytes, oligodendrocytes, ependymal cells). "In particular, the activation of JAK/STAT3 by BACE1 contributes to a feedback loop that perpetuates a pro-tumorigenic and immune-evasive environment within the glioma TME." (PMID 41479886, 2025). "Though the level of the APP gene was not significantly different within the LGG and HGG patients, the high level of the BACE1 gene was positively correlated to the longer survival of glioma patients (p < 0.01)." (PMID 37849438, 2023). "We enrolled TCGA database to analyze the correlation between APP or BACE1 and the OS of glioma patients." (PMID 37849438, 2023). "The expression of the APP gene and the BACE1 gene was positively correlated in the glioma (p < 0.001)." (PMID 37849438, 2023). "Another study that describes the activity of BACE in TME, found that Verubecestat, a BACE1/2 inhibitor promotes an increase in glioma phagocytosis mediated by macrophages, thus hampering tumor growth." (PMID 33926496, 2021). "Herein, we describe the structure elucidation of the new heterocyclic compound, and results from bioassays involving BACE1, human glioma (U251MG) and human pancreatic carcinoma (Panc-1) cells." (PMID 31331110, 2019). "Compounds 1 and 3 showed moderate inhibition of β-secretase 1 (BACE1), whereas 1–9 exhibited moderate to potent inhibition of growth of human glioma (U251) cells." (PMID 31331110, 2019). "BACE1 also modulates the polarization of GAMs through activation of the JAK/STAT3 signaling pathway, a critical driver of immunosuppressive mechanisms in glioma." (PMID 41479886, 2025). "Then, BACE1 in different human and mouse cell lines (HEK293 is a human embryonic kidney cell, U87-MG is a human glioma cell, N2a and bEnd." (PMID 36494704, 2022).
Hypercholesterolemia (5 papers, 2014 to 2022). An increased concentration of cholesterol in the blood. "Aberrant palmitoylation in response to metabolic dysfunction has been suggested to extend BACE1 half life, a theory supported by the colocalization of BACE1 and cholesterol in hypercholesterolemia." (PMID 35119166, 2022). "BACE1 transcription increased in mice feed with high-fat and TC, suggesting that hypercholesterolemia increases the production of Aβ by affecting the activity of secretase." (PMID 31937307, 2020). "Like the statins for hypercholesterolemia, the hope is that a therapeutic window of BACE1 inhibitor doses might be found that reduces cerebral Aβ levels enough for efficacy, yet maintains sufficient BACE1 activity for the avoidance of side effects." (PMID 25621019, 2014).
hyperlipidemia (5 papers, 2019 to 2025). "Hyperlipidemia also elevates the expression of beta-secretase 1 (BACE1)." (PMID 41189817, 2025). "Hyperlipidemia regulates neuronal apoptosis in the hippocampal CA3 of mice by increasing PCSK9 and BACE1 expression, which may elucidate the role of lipid metabolism disorder in AD pathogenesis." (PMID 33192735, 2020).
melanoma (5 papers, 2016 to 2025). A malignant, usually aggressive tumor composed of atypical, neoplastic melanocytes. "A second study, underlining the relevant role of BACE1/2 activity in cancer, describes a paracrine effect of amyloid beta in promoting melanoma brain metastases." (PMID 33926496, 2021). "These experiments clearly point to BACE1/2 as a potential therapeutic target in melanoma and pancreatic adenocarcinoma." (PMID 33926496, 2021). "Very recently, it has been reported that BACE1/2 derived maturation of amyloid beta can drive NETs (Neutrophil Extracellular Traps) deposition in pancreatic cancer and in melanoma." (PMID 33926496, 2021). "In the same study, they also use a dual BACE1/2 inhibitor to block the production of Aβ in vivo, demonstrating the efficacy of this kind of treatment in reducing the number of brain metastases and tumor burden and suggesting BACE1/2 inhibition as new therapy against melanoma progression." (PMID 33926496, 2021).
pancreatic cancer (5 papers, 2012 to 2023). "Recently, Aβ derived from cancer-associated fibroblasts, generated via the cleavage of APP by BACE1/2, was reported to drive neutrophil extracellular traps’ deposition in pancreatic cancer and melanoma." (PMID 38201438, 2023). "The inhibition of BACE1/2 using different inhibitors was shown to reduce the growth and viability of pancreatic cancer cells, suggesting that the cleavage products of APP and amyloid precursor-like protein 2 (APLP2) by BACE1/2 have an important role in cancer cells’ survival and proliferation." (PMID 38201438, 2023). "Notably, it was recently shown that TBO acts as a small molecule capable of inhibiting the proliferation of Hs 766T pancreatic cancer cells by targeting β-secretase 1 (BACE1)." (PMID 38003566, 2023). "The relative contribution of BACE1 and BACE2 to the overall activity of β-secretase in pancreatic cancer cell lines and tissues remains an area of active research." (PMID 22797723, 2012). "Both BACE proteins have been reported in pancreatic tissue, but reports differ on BACE1 and BACE2 expression and activity in pancreatic ductal and acinar cells, which are cell types proposed to give rise to pancreatic cancer." (PMID 22797723, 2012). "The commercially available Calbiochem β-secretase inhibitor has 15 times greater ability to inhibit BACE1 compared to BACE2 (according to the manufacturer) and it required prolonged time in culture to inhibit pancreatic cancer cell survival." (PMID 22797723, 2012). "Ultimately, increased understanding of BACE1 and BACE2 expression and activity in pancreatic cancer will allow optimal selection of β-secretase inhibitors that have greater efficacy in reducing the viability of pancreatic cancer cells." (PMID 22797723, 2012). "Pancreatic cancer, currently lacking definitive treatment options, exhibits elevated levels of APLP2 and its C-terminal fragments (CTFs) which are generated by BACE1." (PMID 38003566, 2023).
atherosclerosis (4 papers, 2017 to 2025). A disease characterized by the build-up of fatty material and calcium deposition in the arterial wall resulting in partial or complete occlusion of the arterial lumen. "ST6Gal‐1 is found at decreased levels in atherosclerosis development, this suggests a role for BACE1 in its regulation." (PMID 35119166, 2022). "This demonstrates the close relationship between BACE1 action, atherosclerosis formation, and cardiovascular disease." (PMID 35119166, 2022). "BACE1 cleavage of ST6Gal‐1, a protein involved in the terminal step of N‐glycan biosynthesis of glycoproteins, contributes to preventing monocyte transendothelial migration, a pivotal mechanism in the initial stages of atherosclerosis." (PMID 35119166, 2022). "This study provides novel insights into the BACE1 protein-degrading pathways in endothelial cells and suggests that inhibiting BACE1 expression may represent a new approach for treating atherosclerosis." (PMID 28091531, 2017). "Thus, inhibition of BACE1 expression may be a new approach for treating atherosclerosis." (PMID 28091531, 2017).
hippocampal atrophy (4 papers, 2020 to 2023). "CSF BACE1 levels were associated with hippocampal atrophy in AD patients." (PMID 37240322, 2023). "The observed BACE1 activity in CSF inversely correlating with hippocampal volume supports the hypothesis that elevated BACE1 may induce downstream amyloidogenic effects by triggering stepwise neurodegeneration leading to hippocampal atrophy." (PMID 33066807, 2020).
Huntington disease (4 papers, 2013 to 2023). Huntington disease (HD) is a rare neurodegenerative disorder of the central nervous system characterized by unwanted choreatic movements, behavioral and psychiatric disturbances and dementia. "MiR-124a is another miRNA which targets BACE1 and has an additional role in excitotoxicity via regulating the glutamate transporter EAAT2 and is itself affected by the Huntington's disease associated transcription factor REST." (PMID 24133413, 2013).
Spinocerebellar Ataxia (4 papers, 2018 to 2026). "Provided are methods and compositions for treatingneurodegenerativediseases including Spinocerebellar Ataxia comprising administeringa BACE1 inhibitor." (PMID 38996083, 2024).
B-vitamin deficiency (3 papers, 2016 to 2025). "Exploiting a nutritional B-vitamin deficiency paradigm, we have previously shown that PSEN1 and BACE1 activity is modulated by one-carbon metabolism, leading to increased amyloid production." (PMID 28973985, 2017). "Another study reported SAM mediated reduction in BACE-1 protein levels under accelerated pathology conditions caused by B-vitamin deficiency but not under normal feeding conditions." (PMID 27681803, 2016).
breast carcinoma (3 papers, 2023 to 2024). "In this study, we focused on the BACE1 knockdown effect on radiosensitization in human cancer cell lines, cervical carcinoma HeLa, breast cancer MDA-MB-231, osteosarcoma U2OS and SAOS cells, and normal human lung fibroblast WI-38 cells." (PMID 38248330, 2024).
heart failure (3 papers, 2013 to 2025). Inability of the heart to pump blood at an adequate rate to meet tissue metabolic requirements. "For example, dysregulation of the BACE1/BACE1-AS/β-amyloid axis was linked to the pathogenesis of heart failure; Aβ is contributory in the development of coronary atherosclerosis and is implicated in the pathophysiology of ischemic heart disease and myocardial ischemia/reperfusion injury." (PMID 35274014, 2022). "While in the cortex of female mice, CHF elicited higher expression of APP; in the hippocampus, heart failure significantly increased the expression of BACE1 and CTFs." (PMID 23737953, 2013). "Interestingly, BACE1 is also involved in the pathological process of other diseases including CVD, given that the dysregulation of the BACE1/Beta‐Secretase‐1 Antisense RNA (BACE1‐AS)/Aβ axis may contribute to the pathophysiology of heart failure." (PMID 39989380, 2025).
hepatocellular carcinoma (3 papers, 2018 to 2025). A malignant tumor that arises from hepatocytes. "Importantly, BACE1-dependent IR cleavage was confirmed in human hepatoma HepG2 cells, which express substantial endogenous IR, showing that it is not restricted to cells ectopically overexpressing IR and/or BACE1." (PMID 29610518, 2018). "The inhibition of oncogenic lncRNA HOTTIP against hepatocellular carcinoma (NCT06544005) and of BACE1/BACE1-AS against heart failure (NCT06213493) is under evaluation." (PMID 40149414, 2025). "We show that in human hepatocellular carcinomas, changes in IRA expression are positively correlated with those of BACE1, implying that these tumors are competent to cleave IR." (PMID 29610518, 2018). "We first examined expression levels of IR and BACE1 in 85 hepatocellular carcinomas and paired the surrounding non-tumor liver tissues." (PMID 29610518, 2018).
Hyperinsulinemia (3 papers, 2020 to 2025). An increased concentration of insulin in the blood. "In addition, PKCι/λ downstream of insulin signaling is hyperactive and increases BACE1-cleavage of APP and Aβ production in hyperinsulinemia." (PMID 40551140, 2025).
ischemic stroke (3 papers, 2012 to 2024). A stroke disorder caused by obstruction of blood flow to the brain, due to thrombotic (local blood clot formation) or embolic (due to a blood clot or other material traveling from another site) event. "BACE1 is a crucial enzyme in Aβ synthesis, and its mRNA and protein levels increase after ischemic stroke." (PMID 38791263, 2024).
vascular dementia (3 papers, 2020 to 2024). A degenerative vascular disorder affecting the brain. "BACE1 activity in serum was found ∼30% higher in patients with AD and vascular dementia (VD) compared to controls." (PMID 38944120, 2024).
age-related macular degeneration (2 papers, 2012 to 2021). Age-related loss of vision in the central portion of the retina (macula), secondary to retinal degeneration. "Taken together, our data show that BACE1 plays a critical role in retinal homeostasis and that the use of BACE inhibitors for AD should be viewed with extreme caution as they could lead to retinal pathology and exacerbate conditions such as age-related macular degeneration." (PMID 22903875, 2012).
amyotrophic lateral sclerosis (2 papers, 2022 to 2024). Amyotrophic lateral sclerosis (ALS) is a neurodegenerative disease characterized by progressive muscular paralysis reflecting degeneration of motor neurons in the primary motor cortex, corticospinal tracts, brainstem and spinal cord. "For instance, FN1 and SIK3 are associated with spondyloepiphyseal dysplasia, PADI2 is related to sclerosis, ERBB4 is connected to amyotrophic lateral sclerosis (ALS), and B3GNT2 and BACE1 are associated with muscular dystrophy and muscular inflammation, respectively." (PMID 38788487, 2024).
atopic dermatitis (2 papers, 2025). "In atopic dermatitis, rare FLG variants interacting with BACE1 suggest a mechanistic bridge between barrier dysfunction and amyloidogenic processing." (PMID 41465136, 2025). "This goes align with the restriction impact of PD98059 on IL-6, NF-κB in an atopic dermatitis model, beside other studies documented the neuroprotective effect of PD98059 against BACE-1 expression in human SH-SY5Y neuroblastoma as well as Aβ precipitation in models of AD." (PMID 40381124, 2025).
attention deficit hyperactive disorder (2 papers, 2022 to 2025). "Neuregulin 1 (nrg1), a substrate of BACE1, is a pre‐synaptic protein thought to be implicated in a number of neurodegenerative diseases and psychiatric/neurodevelopmental disorders such as AD, attention deficit hyperactive disorder (ADHD) and schizophrenia." (PMID 35338546, 2022).
autism (2 papers, 2024). Persistent deficits in social interaction and communication and interaction as well as a markedly restricted repertoire of activity and interest as well as repetitive patterns of behavior. "In our study, VPA-induced autism led to increased oxidative factors, reduced antioxidants, elevated caspase 3, and increased MMP levels, ultimately leading to heightened BACE1 activity." (PMID 39238929, 2024).
brain tumor (2 papers, 2023 to 2025). "Consistent with the high ranking of BACE1 in the screen, and in support of our primary screen findings, activation of its expression with two independent sgRNAs increased metastatic brain tumor burden." (PMID 40601773, 2025). "Additionally, we possessed two matched primary LUAD-BM pairs in our biobank that we were able to interrogate and assess whether BACE1 expression was preserved from primary to metastatic brain tumor." (PMID 40601773, 2025). "Importantly, BACE1 levels correlated with erythrophagocytosis and inflammatory gene expression in vitro and in vivo, consistent with previous findings obtained from LPS-induced inflammatory disorders and brain tumor microglia." (PMID 37552127, 2023).
cerebral atherosclerosis (2 papers, 2017 to 2018). Atherosclerosis of the cerebral vasculature. "Accordingly, BACE1 levels are not enhanced in individuals with cerebral atherosclerosis, a potential marker for preclinical AD and thus BACE1 levels seem to increase in parallel with β-amyloid deposition, but not before." (PMID 29327084, 2018).
cerebrovascular disease (2 papers, 2007 to 2020). "BACE1 levels are elevated under a variety of conditions, including those cellular changes evoked under the stressful conditions of cardio- and cerebrovascular disease." (PMID 18005427, 2007). "In addition to exerting causative effects on the vasculature, alterations in Aβ levels may occur as a consequence of cardio- and cerebrovascular disease, possibly via a mechanism involving BACE1 elevations." (PMID 18005427, 2007). "BACE-1 dysregulation together with AD pathology accumulation might be the cornerstone of both LOAD (no/minimal cerebrovascular disease) and VAD (significant cerebrovascular disease); at this point, the real existence of pure VAD from the nosological point of view could be at least questionable." (PMID 32917964, 2020).